FUT8 (fucosyltransferase 8)
Diseases named in the same sentence as FUT8 in open-access papers (continued):
Sharing a sentence is not in itself a finding about the gene and the disease.
prostate carcinoma (continued). "However, it was unclear how prostate cancer cells manage to escape cell death by upregulating the FUT8 gene expression in the androgen-depleted environment and if testosterone (R1881) was negatively affecting the FUT8 levels." (PMID 32085441, 2020). "Similarly, our initial studies with FUT8 in prostate cancer specimens demonstrated a strong correlation between FUT8 expression and aggressive prostate cancer." (PMID 32085441, 2020). "Further studies will be needed to understand how FUT8 overexpression might be driving multiple drugs-resistant mechanisms to support prostate cancer cell growth." (PMID 32085441, 2020). "In order to investigate whether FUT8 expression was colocalized with the EGFR protein in prostate cancer cells, we performed an immunofluorescence (IF) colocalization study using confocal microscopy." (PMID 32085441, 2020). "Taken together, these data confirm our in vitro qPCR and LC–MS/MS protein expression data that FUT8 overexpression might be driving the castration-dependent EGFR regulation in prostate cancer." (PMID 32085441, 2020). "In this study, we discovered a novel role of FUT8 overexpression, which might be responsible for driving castration resistance in prostate cancer." (PMID 29339807, 2018). "Similarly, in prostate cancer, we have previously observed and reported higher FUT8 expression in aggressive tumors (Gleason 8 and above) compared to its non-aggressive Gleason 6 and lower." (PMID 29339807, 2018). "However, when LNCaP cells were grown in charcoal-stripped media for several passages (LNCaP-95), there was an increase in the FUT8 expression indicating androgen ablation as a requisite for the FUT8 overexpression in the AR-positive prostate cancer cells." (PMID 29339807, 2018). "In addition, we have also reported that overexpression of FUT8 in prostate cancer cells was correlated with increased fucosylation of glycoproteins in aggressive prostate cancer cells." (PMID 29339807, 2018). "Interestingly, we had previously shown negligible levels of FUT8 expression in LNCaP cells compared to the more aggressive PC3 prostate cancer cells." (PMID 29339807, 2018). "To further determine whether androgen ablation was indeed responsible for the overexpression of FUT8 in prostate cancer, we moved to a more biological relevant mice model." (PMID 29339807, 2018). "In the prostate, only Fut8 is expressed by the prostate cancer cell lines PC3 and DU145." (PMID 27494861, 2016). "To further investigate whether overexpression of FUT8 in androgen-resistant prostate cancer cells was due to the upregulation of FUT8 mRNA, we analyzed the LAPC4-AI and LAPC4 wild-type cells along with the LNCaP and LNCaP-95 prostate cancer cell lines using qRT-PCR analysis." (PMID 29339807, 2018). "Further studies are underway in the laboratory to understand whether FUT8 overexpression acts as a driver in the development of castration-resistant phenotypes, which may be used as a therapeutic target to overcome prostate cancer resistance to anti-androgen-based therapies." (PMID 29339807, 2018). "Similarly, we also demonstrated that overexpression of FUT8 might be responsible for the decreased PSA expression in prostate cancer specimens." (PMID 29339807, 2018). "FUT8 is expressed in PC3 and DU145—prostate cancer cell lines, normal prostate epithelial cells (PrECs), and normal prostate stromal cells (PrSCs)." (PMID 33466384, 2021). "Altered expression of FUT8 and FUT6 is an important feature in several cancers such as high-grade prostate cancer and breast cancer." (PMID 34359624, 2021). "Recent studies have shown that aberrant expression of α fucosyltransferase (FUT8), which catalyzes the transfer of fucose from GDP-fucose to core-GlcNAc of the N-linked glycoproteins, modulates cellular behavior that could lead to the development of aggressive prostate cancer." (PMID 29339807, 2018).
prostate carcinoma (continued). "The relative quantitative mRNA analysis from wild types (LNCaP and LAPC4) and the androgen-resistant prostate cancer cells (LNCaP-95 and LAPC4-AI) revealed overexpression of FUT8 in both androgen-resistant prostate cancer cell lines." (PMID 29339807, 2018). "To further confirm these findings, we evaluated 10 different metastatic prostate cancer tissues for PSA and FUT8 expression using western blot analysis." (PMID 29339807, 2018). "Previous studies have suggested that FUT8 can be repressed by androgens, and consistent with this, we detected an increase in FUT8 levels in clinical samples from patients treated with ADT and a decrease in FUT8 levels in prostate cancer cells stimulated with androgens." (PMID 40387385, 2025). "Furthermore, analysis of the TCGA PRAD cohort revealed a significant correlation between expression of FUT8 and genes for IGFBP5, IL1B and PTGES3 in clinical prostate cancer tissue." (PMID 40387385, 2025). "Based on our knowledge, this is the first report that describes how FUT8 in an androgen-depleted condition might be driving the expression of EGFR and rescuing prostate cancer cells from depleted androgen-induced cell death." (PMID 32085441, 2020). "Based on our knowledge, this is the first report that describes how FUT8 in androgen-depleted condition might be driving the expression of EGFR and rescuing prostate cancer cells from depleted androgen-induced cell death." (PMID 32085441, 2020). "In addition to the increase in core fucosylation, the transcription of FUT8 was enhanced in HCC and prostate cancer tissues." (PMID 31168300, 2019). "Here we report that FUT8 overexpression was induced in castration-resistant cells and was responsible for the lower prostate-specific antigen (PSA) production and cell survival in prostate cancer." (PMID 29339807, 2018). "To further demonstrate whether FUT8 overexpression in prostate cancer cells promotes the proliferation of cells in normal or androgen-ablated conditions, we preformed the MTS assay on the LAPC4 cells that were stably selected to overexpress FUT8 (LAPC4-FUT8) or control vectors (LAPC4 Ctr)." (PMID 29339807, 2018).
colorectal cancer (19 papers, 2016 to 2025). A primary or metastatic malignant neoplasm that affects the colon or rectum. "The inferred mechanism is that the low expression of FUT8 in TNM stages IV or microsatellite stable colorectal cancer may cause E-cadherin to decrease or be truncated, resulting in decreased tumor cell-cell adhesion and increased metastasis." (PMID 33323540, 2020). "Our findings highlight the importance of the FUT8 gene in the development of colorectal cancer and suggest the potential of VE-822 as a treatment for colon cancer." (PMID 40729369, 2025). "Specifically, in the cellular model of colorectal cancer (CRC) progression formed using the human syngeneic lines SW480 and SW620, knockdown of the FucT-8-encoding FUT8 gene significantly enhanced TRAIL-induced apoptosis in SW480 cells." (PMID 37569254, 2023). "Studies frequently reported that FUT8 is highly expressed in many malignant diseases, such as lung, breast, and colorectal carcinomas, but it is negatively correlated with the development of gastric cancer." (PMID 33520694, 2020). "The upregulation of FUT8 activity and global fucosylation has been observed in malignant tumors, including hepatic, lung, thyroid, and colorectal cancer, and is closely related to the severity of these cancers by affecting tumor size, metastases, invasion, and prognosis." (PMID 34336817, 2021). "By integrating data from immunohistochemical analysis of colorectal cancer patient tissues and colorectal cancer disease staging from the HPA database, we selected FUT8 as the target gene for further study." (PMID 40729369, 2025). "Disruption of the glycosylation machinery is a commonfeature inmany types of cancer, and colorectal cancer (CRC) is no exception.Core fucosylation is mediated by the enzyme fucosyltransferase 8 (FucT-8),which catalyzes the addition of α1,6-l-fucose to theinnermost GlcNAc residue of N-glycans." (PMID 38507902, 2024). "Circ_0001998, a newly discovered circRNA, is derived from the FUT8 (fucosyltransferase 8) gene, which may be related to the development of colorectal cancer, but its role in LUAD has not been reported." (PMID 35600959, 2022). "We compared the ratio of TRAIL-mediated apoptosis in knockdown clones for FUT8 mRNA (F52L and F59L) with respect to their corresponding transduction controls (NTC: non-targeted controls) and wild-type (wt) SW480 and SW620 colorectal cancer (CRC) cells." (PMID 37569254, 2023).
emphysema (16 papers, 2010 to 2025). "In Fut8−/− mice and cigarette smoke-exposed Fut8+/− mice, core-fucosylation has been implicated in the development of emphysema." (PMID 35670884, 2022). "One autopsy report implied an association of the Thr267Lys polymorphism of Fut8 gene with pulmonary emphysema." (PMID 35670884, 2022). "FUT8-deficient mice exhibited an emphysema-like phenotype associated with the decreased expression of VEGFR2." (PMID 34069424, 2021). "The level of core fucosylation has also been implicated in the development of emphysema in Fut8−/− mice and cigarette smoke-exposured Fut8+/− mice." (PMID 32900381, 2020). "FUT8 encodes an enzyme belonging to the family of fucosyltransferases, and homozygous deletion of this gene in mouse shows emphysema-like changes in the lung." (PMID 28201986, 2017). "Fut8 knockout (Fut8-/-) mice exhibited emphysema-like changes in the lung, and Fut8 knockdown (Fut8+/-) mice exposed to cigarette smoke were found to be more susceptible to developing emphysema than wild-type mice." (PMID 37256139, 2023). "FUT8 Thr267Lys mutation is also a risk factor for emphysema." (PMID 37256139, 2023). "A phenotype of FUT8 knock-out mice is at high risk of developing emphysema in the lungs." (PMID 34943050, 2021). "Additionally, defects in core fucosylation have been associated with abnormal lung development and an emphysema-like phenotype in Fut8 deficient mice." (PMID 20532047, 2010). "Fut8−/− mice showed an emphysema-like pulmonary disorder because of an aberration in transforming growth factor beta 1 receptor activation and downstream signaling pathway." (PMID 38042483, 2023). "Consistently, the Fut8+/− mice exhibited greater sensitivity to cigarette smoke–induced emphysema than the Fut8+/+ mice." (PMID 38042483, 2023). "FUT8 disruption leads to growth retardation, early postnatal developmental death, and emphysema-like changes in the lungs." (PMID 37805653, 2023). "FUT8 knockout (FUT8-/-) mice exhibit early postnatal death, retardant growth, emphysema-like changes, schizophrenia-like phenotype and so on." (PMID 35401499, 2022). "The core fucosylation is required for TGFB1 function as shown by data from Fut8 KO mice, whose emphysema-like phenotype can be explained by impaired TGFB signaling." (PMID 29462882, 2018). "As expected by the widespread expression and abundance of core fucose, Fut8 (Fut8)-null mice show multiple phenotypes including semilethality, the development of emphysema, dysfunction in the brain and impaired immunity." (PMID 27136596, 2016). "Moreover, in a cigarette smoke-induced emphysema model, Fut8+/− mice were more sensitive than Fut8+/+ mice." (PMID 39864626, 2025). "In addition, Fut8+/− mice exhibited a more significant increase in sensitivity to a cigarette smoke–induced emphysema model than Fut8+/+ control mice." (PMID 38042483, 2023). "Indeed, genetic inactivation of Fut8 led to emphysema, severe growth retardation and early postnatal lethality in mice." (PMID 35303925, 2022). "Mice KO for the core fucose synthesizing enzyme Fut8 display an emphysema-like phenotype." (PMID 29462882, 2018). "Previous research indicated that a lack of core fucosylation leads to emphysema-like changes in Fut8−/− mice." (PMID 39864626, 2025). "In spite of these studies in Fut8−/− mice, the precise roles of Fut8 in alveologenesis during lung development and the formation of emphysema in lung diseases have not been investigated in detail either at cellular or molecular levels." (PMID 32900381, 2020).
non-small cell lung carcinoma (14 papers, 2013 to 2024). A group of at least three distinct histological types of lung cancer, including non-small cell squamous cell carcinoma, adenocarcinoma, and large cell carcinoma. "For example, in non-small cell lung cancer, FUT8 expression is up-regulated and is associated with tumor metastasis and a reduced prognosis for patients with non-small cell lung cancer." (PMID 37724903, 2023). "FUT8 overexpression is also observed in cancer-associated fibroblasts (CAFs) in non-small-cell lung carcinoma, and FUT8 in CAFs promotes the formation of an invasive and malignant tumor microenvironment via core fucosylation of EGFR." (PMID 34948129, 2021). "Furthermore, downregulation of E-cadherin and nuclear translocation or activation of β-catenin/LEF-1, a major signaling event occurring in EMT, was found associated with FUT8 upregulation during non-small cell lung cancer progression." (PMID 28982386, 2017). "miR-198 also acts as a direct negative regulator of FUT8 expression both in a colorectal and a non-small cell lung cancer model, with miR-198 inhibition leading to an aggressive phenotype and a survival disadvantage." (PMID 36980181, 2023). "FUT8 was up-regulated in non-small cell lung cancer and promoted the process of epithelial–mesenchymal transition." (PMID 34221996, 2021). "When A549 cells (a human non-small cell lung cancer cell line) are depleted of FUT8, EGFR fucosylation is reduced, as is EGF-mediated cellular growth response and sensitivity." (PMID 33466384, 2021). "FUT8 is up-regulated in non-small cell lung cancer (NSCLC) and is correlated with tumour metastasis, disease recurrence and poor survival in patients." (PMID 33466384, 2021). "Moreover, the aberrant upregulation of FUT8 in non-small-cell lung cancer was reported to be correlated with the poor clinical outcomes, suggesting the involvement of Fut8 in cancer development and its potential as biomarker." (PMID 27136596, 2016). "Similarly, the development of an invasive and malignant tumor microenvironment was facilitated by FUT8-mediated CF in fibroblasts connected with cancer, and the ensuing non-small cell lung cancer cells showed accelerated proliferation and increased invasiveness." (PMID 37724903, 2023). "Another important process shown to be related to FUT8 up-regulation is the epithelial-to-mesenchymal transition (EMT), studied in the context of non-small cell lung cancer (NSCLC)." (PMID 36980181, 2023). "The expression of FUT8 is elevated in non-small-cell lung cancer (NSCLC), and the expression of FUT8 is related to the tumour metastasis, tumour stage (N0), male sex, disease recurrence and a poor survival rate of NSCLC patients 21, 41-42." (PMID 34093814, 2021). "FUT8 upregulation is not observed in hepatocarcinoma only, but it is overexpressed also in several malignant tumors, including ovarian, thyroid, colorectal and non small cell lung cancer." (PMID 24130780, 2013).
liver cancer (10 papers, 2014 to 2025). An epithelial or non-epithelial malignant neoplasm that arises from the liver. "Hsa_circ_0001998, also known as circRNA FUT8, is overexpressed in liver cancer and promotes disease progression by sponging miR-548c." (PMID 40626007, 2025). "Yanru Guo’s team conducted a study on liver cancer, revealing that a high level of FUT8 expression leads to an enhanced core fucosylation of Hsp90." (PMID 38256141, 2024). "For instance, hepatitis C virus infection with human liver cancer line Huh7.5.1 leads to upregulated FUT8 expression, resulting in cell proliferation and drug resistance." (PMID 38256141, 2024). "FUT8 transcription in liver cancer involves the indirect (through Hsp90 and MUC1) activation of the STAT3/JAK1 cascade, which is potentiated by antisense RNA HOTAIR." (PMID 36555445, 2022). "We next asked if Fut8 expression is affected during liver cancer progression." (PMID 24927126, 2014). "We and others have shown that core fucosylation, catalyzed by alpha-1,6-fucosyltransferase (FUT8), is one of the main N-glycan modifications in early liver disease like nonalcoholic fatty liver disease and liver cancers." (PMID 36890858, 2023). "Inhibition of FUT8 can weaken hepatocyte epidermal growth factor (EGF) and hepatocyte growth factor (HGF), and thus reduce the incidence of liver cancer." (PMID 35410157, 2022). "This is the case of liver cancer, in which miR-9 modulates GALNT4 and ST6GAL1, miR-122 modulates FUT8 and GALNT10 and miR-34 modulates ST3GAL5 and FUT8." (PMID 36555445, 2022).
gastric cancer (9 papers, 2014 to 2025). A primary or metastatic malignant neoplasm involving the stomach. "In contrast, the expression of FUT8 is downregulated in gastric cancer, and the upregulation of FUT8 is associated with a better overall survival rate of GC patients." (PMID 34093814, 2021). "In our gastric cancer patients’ tissues, we found downregulated expression of Fut8 in cancer tissues compared to matched normal tissues in over 80% of patients (data not shown)." (PMID 37612293, 2023). "Consistently, lens culinaris agglutinin (LCA)-binding proteins were decreased significantly in sera of gastric cancer, and protein level of Fut8 was decreased significantly in gastric tumor tissues compared with that in adjacent non-tumor tissues." (PMID 24732908, 2014). "The recombinant plasmids of GDP-fucose transporter and α-1,6-fucosyltransferase (Fut8) were constructed and transfected into gastric cancer cell lines BGC-823 and SGC-7901." (PMID 24732908, 2014). "With Fut8 overexpression in gastric cancer cells, cell growth decreased." (PMID 37612293, 2023). "In gastric cancer, fucosylation and Fut8, a main fucosyltransferase in cancer, were downregulated." (PMID 37612293, 2023). "Interestingly, unlike other tumours, the expression of FUT8 is decreased in gastric cancer, and the upregulation of FUT8 expression can inhibit the proliferation of human gastric cancer cells." (PMID 34093814, 2021). "We found that the up-regulated GDP-Tr and Fut8 expression in human gastric cancer cells could lead to low proliferation." (PMID 24732908, 2014). "FUT8 and/or core fucosylated proteins are frequently upregulated in liver, lung, colorectal, pancreas, prostate,breast, oral cavity, oesophagus, and thyroid tumours, diffuse large B-cell lymphoma, ependymoma, medulloblastoma and glioblastoma multiforme and downregulated in gastric cancer." (PMID 34093814, 2021). "To understand the molecular mechanisms underlying the increase in AFP-L3 levels in the sera of patients with HCC, we purified alpha-1-6-fucosyltransferase (FUT8) from the porcine brain and the conditioned medium of a human gastric cancer cell line." (PMID 37108200, 2023).